BMP2 (bone morphogenetic protein 2)
Diseases named in the same sentence as BMP2 in open-access papers (continued):
Sharing a sentence is not in itself a finding about the gene and the disease.
endometriosis (3 papers, 2016 to 2024). The growth of functional endometrial tissue in anatomic sites outside the uterine body. "Using 3-dimensional models of endometrial stromal and epithelial assembloids, we showed that exogenous BMP2 improved decidual marker expression in individuals with endometriosis." (PMID 37986901, 2023). "Our findings indicate that BMP2 and the downstream activated signaling pathways are defective in the endometrium of patients with endometriosis and that BMP2 supplementation may correct the defect." (PMID 38402336, 2024). "To test whether the addition of recombinant BMP2 supplementation could restore the decidual response in the endometrium from individuals with endometriosis, we added BMP2 to endometrial stromal cell cultures and to 3-dimensional endometrial stromal/epithelial co-cultures, or “assembloids”." (PMID 38402336, 2024). "Gene expression analysis using RT-qPCR demonstrated decidual markers such as BMP2 and IGFBP1 showed increasing levels throughout Day 2 to Day 8 EPC treatment in the stromal cells with blunted induction in the endometriosis cells." (PMID 38402336, 2024). "We found that relative to EPC treatment alone, the addition of BMP2 + EPC increased the expression of canonical decidual genes in both the stromal cell and assembloid cultures of endometrium from individuals with endometriosis." (PMID 38402336, 2024). "Similar to BMP2, the ID1 and ID3 genes were progressively increased over the time course treatment in the samples derived from donors without endometriosis while they were conversely downregulated in the endometriosis cohort." (PMID 38402336, 2024).
Familial adenomatous polyposis (3 papers, 2011 to 2015). Familial adenomatous polyposis (FAP) is characterized by the development of hundreds to thousands of adenomas in the rectum and colon during the second decade of life. "In patients with familial adenomatous polyposis, BMP-2 can also block cell growth while promoting apoptosis of mature epithelial cells." (PMID 25897433, 2015). "BMP2 expression was lost in microadenoma of familial adenomatous polyposis, while BMP2 was expressed in mature colonic epithelial cells, promoting apoptosis and differentiation and inhibiting proliferation." (PMID 22072987, 2011).
fracture (3 papers, 2021 to 2023). "In summary, these results indicate that PS promotes bone formation through the upregulation of BMP-2 signaling, resulting in effective bone union in a rat femoral fracture model." (PMID 37108563, 2023). "Although several BMPs, for example BMP-2 and BMP-4, possess excellent osteogenic properties, their levels remain very low in the peripheral blood after a bone fracture." (PMID 33833129, 2021). "In addition, treatment with PS was found to enhance BMP-2/Smad signaling, which plays an important role in the mechanism of differentiation of MC3T3-E1 cells, which are osteoblast progenitor cells, and in bone fracture animal models." (PMID 37108563, 2023).
head and neck squamous cell carcinoma (3 papers, 2016 to 2024). A squamous cell carcinoma that arises from any of the following anatomic sites: lip and oral cavity, nasal cavity, paranasal sinuses, pharynx, larynx, and salivary glands. "In addition, head and neck squamous cell carcinomas with high baseline BMP-2 protein levels are associated with higher rates of local recurrence." (PMID 27636990, 2016). "We used the GSVA package in R software to analyze the head and neck squamous cell carcinoma (HNSCC) data from TCGA, and found that the expression of BMP2 was positively correlated with the PI3K-AKT pathway, angiogenesis, and EMT-markers." (PMID 38610001, 2024).
Hirschsprung disease (3 papers, 2019 to 2021). Hirschsprung disease (HSCR) is a congenital intestinal motility disorder that is characterized by signs of intestinal obstruction due to the presence of an aganglionic segment of variable extent in the terminal part of the colon. "The expression of BMP2 is significantly attenuated in Hirschsprung’s disease patients—which results from defects in NCCs colonizing the intestines—and leads to an absence of enteric ganglia in the colon." (PMID 34426786, 2021). "BMP2 was also found to be required for the migration of NCC in the enteric nervous system in the zebrafish and to be significantly decreased in the gut of patients affected by Hirschsprung's disease, a disease characterized by deficient enteric NCC migration." (PMID 32914578, 2020).
hyperandrogenemia (3 papers, 2012 to 2022). "Our study shows that the BMP-2 secreted by BM-hMSC can treat hyperandrogenemia by suppressing steroidogenesis and gene expression." (PMID 34502090, 2021). "Together, these studies suggest that BMP-2 may reverse hyperandrogenemia in PCOS." (PMID 34502090, 2021). "Previous studies have shown that several BMPs, including BMP2, BMP4, BMP5, BMP6, BMP7 and BMP8A are expressed in the granulosa cells from normally cycling and polycystic ovary syndrome women." (PMID 35395768, 2022).
hyperlipidemia (3 papers, 2015 to 2016). "Using the drug repositioning strategy, Mundy and colleagues identified that statins that are commonly prescribed for hyperlipidemia enhance the BMP2 promoter activity." (PMID 26844285, 2015).
ischemia (3 papers, 2020 to 2023). A hypoperfusion of the BLOOD through an organ or tissue caused by a PATHOLOGIC CONSTRICTION or obstruction of its BLOOD VESSELS, or an absence of BLOOD CIRCULATION. "We used adenoviral vector-mediated intramyocardial delivery of BMP2 in pig myocardium 14 days post-ischemia operation." (PMID 38028463, 2023). "BMP in the SVZ stem cell niche is rapidly upregulated after traumatic injury and BMP-2 is rapidly and strongly increased after photothrombotic ischemia (this study)." (PMID 34698916, 2022). "Our results indicate that BMP2 does not improve heart function after ischemia or promote beneficial outcomes, such as angiogenesis, nor cardioprotective features." (PMID 38028463, 2023). "The correlation between the increased level of BMP-2 and high levels of MMP-9 and hCRP observed on Days 1 and 7 after MI, as well as at the six-month follow-up, most likely indicates that BMP-2 is an active driver of the myocardium inflammation under ischemia conditions." (PMID 32992577, 2020).
joint disease (3 papers, 2006 to 2023). "It is also surprising that the young (FAI) and older (OA) age groups with joint disease show tissue differentiation results that are, at 6 weeks, significantly higher than in the normal adult group in the BMP-2 treated patient pool." (PMID 37365169, 2023). "They compared synovium from RA and spondyloarthropathies with synovium from traumatic joint diseases and found BMP-2 and BMP-6 to be expressed most consistently with a calculated relative expression in the range 0.002 to 0.2% compared with β-actin." (PMID 16542506, 2006). "It is also noteworthy that the collagen XI gene expression levels of the two groups with joint diseases (FAI, OA) show highest levels in the BMP-2/TGF-β1combined groups, at least in the initial stimulation phase at 2 weeks." (PMID 37365169, 2023).
leiomyoma (3 papers, 2020 to 2023). A well-circumscribed benign smooth muscle neoplasm characterized by the presence of spindle cells with cigar-shaped nuclei, interlacing fascicles, and a whorled pattern. "TGF-β is known to be elevated in leiomyomas and acts as a diffusible signaling molecule to alter bone morphogenetic protein 2 (BMP-2), reducing HOXA-10 expression throughout the endometrium." (PMID 33291422, 2020). "The same groups subsequently showed that TGF-β3 is elevated in leiomyoma-conditioned media, leading to repression of BMP receptor types 1B and 2 and eventually a lack of response to BMP-2." (PMID 34640407, 2021).
nasopharyngeal carcinoma (3 papers, 2017 to 2024). A carcinoma arising from the nasopharyngeal epithelium. "High BMP2 expression is significantly associated with clinical stage, distant metastasis, and shorter survival in patients with nasopharyngeal carcinoma." (PMID 35693928, 2022). "In nasopharyngeal carcinoma, the overexpression of BMP2 has been reported to enhance tumor cell invasion and EMT through the mTORC1 signaling pathway." (PMID 38610001, 2024). "The mTORC1 inhibitor rapamycin blocks BMP-2-induced EMT in nasopharyngeal carcinoma cells." (PMID 35693928, 2022).
Osteochondroma (3 papers, 2015 to 2023). A common, benign cartiliginous neoplasm arising from the metaphysis of bone. "For example, the involvement of BMP2 signalling in the growth of the cartilage cap in osteochondroma has been demonstrated." (PMID 36162830, 2023). "BMP-2 and BMP-4, which are markers of osteogenesis and chondrogenesis, respectively, were consistently positive in BPOP but only weakly positive in osteochondroma." (PMID 26865041, 2016). "Pathological diagnosis was osteochondroma; immunohistochemistry showed that the tumor exhibited a conspicuous expression of BMP-4 and BMP-2 but rarely expression of PCNA." (PMID 25664314, 2015). "IHC staining for osteogenetic protein expression in the BPOP specimen was conspicuously positive for both BMP-2 and BMP-4, which are known to indicate osteogenesis and chondrogenesis, respectively, while osteochondroma was much more weakly positive for these proteins." (PMID 26865041, 2016).
Parkinson disease (3 papers, 2020 to 2022). A progressive degenerative disorder of the central nervous system characterized by loss of dopamine producing neurons in the substantia nigra and the presence of Lewy bodies in the substantia nigra and locus coeruleus. "Ongoing diagnostic studies, however, have revealed that a large number of small molecule drugs that trigger the BMP2-Smad signaling pathway with an osteogenic nature may be effective in Parkinson's disease treatment." (PMID 36545269, 2022).
radiculopathy (3 papers, 2020 to 2023). Disease involving a spinal nerve root (see spinal nerve roots) which may result from compression related to intervertebral disk displacement; spinal cord injuries; spinal diseases; and other conditions. "There were no late complications related to BMP-2 such as ectopic bone formation or radiculopathy or tumor formation during 2-year postoperative follow up." (PMID 37337174, 2023).
renal cell carcinoma (3 papers, 2010 to 2015). "We investigated whether impaired regulation of bone morphogenetic protein-2 (BMP-2) via epigenetic pathways is associated with renal cell carcinoma (RCC) pathogenesis." (PMID 25797254, 2015). "In agreement with our finding is the case report describing detection of BMP-2 and ossification in renal cell carcinoma." (PMID 23675191, 2010).
tooth agenesis (3 papers, 2016 to 2021). A tooth disease characterized by failure to develop one or more missing teeth. "The rs235768 in BMP2 was associated with tooth agenesis in univariate and multivariate analysis (p < 0.001)." (PMID 34539446, 2021). "The allele T of the rs235768 in BMP2 was associated with higher chance to present tooth agenesis in comparison with control group (p < 0.001; PR = 3.45; 95% CI = 2.54–4.70)." (PMID 34539446, 2021). "All haplotypes formed by the rs235768 and rs1005464 polymorphisms in BMP2 were associated with tooth agenesis and tooth agenesis subgroups (p < 0.001)." (PMID 34539446, 2021). "Nevertheless, in another study, one novel BMP2 gene mutation was found in association with tooth agenesis." (PMID 27362534, 2016). "In Chinese populations, as far as we know, two studies have focused on genetic variations of BMP2 and the risk of tooth agenesis." (PMID 27362534, 2016). "Our results showed that rs15705 and rs3178250, located at the 3′-UTR of the BMP2 gene, are potentially associated with non-syndromic tooth agenesis." (PMID 27362534, 2016). "Therefore, genetic variants of BMP2 are potentially susceptibility factors for non-syndromic tooth agenesis." (PMID 27362534, 2016). "For instance, two mutations of BMP2 were detected in two Mexican families with tooth agenesis." (PMID 27362534, 2016). "Associations between the four BMP2 SNPs and tooth agenesis susceptibility." (PMID 27362534, 2016). "Overall, four potentially functional SNPs of BMP2 (rs15705, rs235768, rs235769 and rs3178250) were selected, and their associations with the susceptibility of tooth agenesis were evaluated in a case-control study of 335 non-syndromic tooth agenesis cases and 444 healthy controls." (PMID 27362534, 2016). "In conclusion, our study suggested that genetic polymorphisms in BMP2 and SMAD6 are involved in a higher chance to present isolated tooth agenesis." (PMID 34539446, 2021). "For the rs235768 in BMP2, patients carrying TT genotype have higher chance to present tooth agenesis [p < 0.001; prevalence ratio (PR) = 8.29; 95% confidence interval (CI) = 4.26–16.10]." (PMID 34539446, 2021). "In conclusion, genetic polymorphisms in BMP2 and SMAD6 were associated with isolated tooth agenesis." (PMID 34539446, 2021). "Taken together, our study indicated that rs15705 and rs3178250, located at the BMP2 3’-UTR and potentially affecting the miRNA-mRNA interaction, are associated with an increased risk of non-syndromic tooth agenesis." (PMID 27362534, 2016). "The aim of the present study was therefore to investigate the roles of the potentially functional SNPs of BMP2 in the occurrence of tooth agenesis." (PMID 27362534, 2016). "Interestingly, genetic polymorphisms in BMP2 and BMP4 have been associated with both, isolated tooth agenesis and oral clefts." (PMID 34539446, 2021). "In the present study, we designed an ongoing hospital-based case-control study and selected four potentially functional SNPs of BMP2 to explore their associations with the risk of non-syndromic tooth agenesis." (PMID 27362534, 2016). "Previous studies have tried to investigate the genetic contributions of BMP2 in the family or in sporadic non-syndromic tooth agenesis, but the results were not consistent." (PMID 27362534, 2016).
triple-negative breast carcinoma (3 papers, 2023 to 2025). An invasive breast carcinoma which is negative for expression of estrogen receptor (ER), progesterone receptor (PR), and human epidermal growth factor receptor 2 (HER2). "To explore whether BMP2 could serve as a substrate for the development of breast MCA, we compared the expression level of BMP2 in breast MCA with that in triple-negative breast cancer (TNBC) and the histology of IDC by immunohistochemistry." (PMID 40936753, 2025). "ANLN is also upregulated in triple-negative breast cancer(TNBC), where it enhances cancer stemness and promotes sphere formation via the TWIST1 and BMP2 signaling pathways." (PMID 41573677, 2025).
acromegaly (2 papers, 2021). Acromegaly is an acquired disorder related to excessive production of growth hormone (GH) and characterized by progressive somatic disfigurement (mainly involving the face and extremities) and systemic manifestations. "When analyzed separately, gingival BMP-2 levels revealed a causal relation with the degree of periodontal pathology with borderline significance only in patients with acromegaly (p = 0.057)." (PMID 33421969, 2021). "In this context, we aimed to determine BMP-2 and BMP-4 levels in the gingival fluid to find any association with the health status of the periodontal tissue in those with acromegaly." (PMID 33421969, 2021). "In our present study, although the gingival BMP2 levels tend to be higher in those with healthier periodontal tissue, gingival BMP-2 and BMP-4 levels were similar in the active and inactive acromegaly patients." (PMID 33421969, 2021). "Gingival BMP-2 and BMP-4 levels were similar in the acromegaly and control groups." (PMID 33421969, 2021).
acute kidney injury (2 papers, 2017 to 2021). Sudden and sustained deterioration of the kidney function characterized by decreased glomerular filtration rate, increased serum creatinine or oliguria. "BMP-2 also appears to play an important role in the regeneration of tubular cells; increased BMP-2 expression in the course of acute kidney injury was shown to induce the myofibroblastic transition in renal progenitor cells." (PMID 34768412, 2021).
age-related macular degeneration (2 papers, 2020 to 2021). Age-related loss of vision in the central portion of the retina (macula), secondary to retinal degeneration. "Remarkably, human ocular samples from neovascular age-related macular degeneration (AMD) donors were rich in BMP2 and BMP4, particularly in RPE and choroid rather than in retina." (PMID 33919531, 2021).
androgenetic alopecia (2 papers, 2025). "Bone morphogenetic protein 2 (BMP‐2) is typically downregulated in patients with androgenetic alopecia (AGA)." (PMID 41323822, 2025). "Research on androgenetic alopecia has shown that ADSC‐exosomes can promote DPC proliferation and increase the expression of cyclins, β‐catenin, versican, and BMP2." (PMID 40501302, 2025).
aortic valve stenosis (2 papers, 2014 to 2024). Aortic valve stenosis (AVS) is a condition characterized by narrowing of the heart's aortic valve opening. "Excitingly, injection of AAV2-circHIPK3 in the CAVD model mice alleviated aortic valve stenosis, decreased thickness and calcium deposition in the aortic valve leaflets, and downregulated BMP-2 expression." (PMID 38945954, 2024). "The pro-osteogenic role of BMP-2- Smad1/5/8 has been shown in human aortic valve interstitial cells from patients with calcifying aortic valve stenosis." (PMID 24586576, 2014).
Autoimmunity (2 papers, 2016 to 2022). The occurrence of an immune reaction against the organism's own cells or tissues. "Both NK activation and autoimmunity are linked to BMP signaling, e.g., via an autocrine activation pathway via BMP receptors and BMP ligands in NK cells, which fits our identified target genes BMP1, BMP2, BMP3, BMP7, BMP6, BMPER, BMPR1B, and, most importantly, BMPR2." (PMID 35455956, 2022).
Barrett esophagus (2 papers, 2012 to 2022). Esophageal lesion lined with columnar metaplastic epithelium which is flat or villiform. "BMP-2 is a negative regulator of hepatocyte proliferation downregulated in the regenerating liver, although in the oesophagus BMP-2 production may actually be implicated in induction of the precancerous condition Barrett's esophagus." (PMID 22315590, 2012).
basal cell carcinoma (2 papers, 2017 to 2025). A carcinoma involving the basal cells. "Pathways that followed were ligand-receptor interactions (IHH, PTCH1) (p-value = 5.76 × 10−5) and signalling in basal cell carcinoma (BMP2, STK36, PTCH1) (p-value = 6.73 × 10−5)." (PMID 28117334, 2017).
bladder tumors (2 papers, 2022 to 2025). "In our experimental models, we employed the BMP2 inhibitor Dorsomorphin in mice with bladder tumors and observed a significant inhibition of tumor progression." (PMID 40552583, 2025).
brachydactyly (2 papers, 2022 to 2025). A disease characterized by the presence of brachydactyly, including syndromic and non-syndromic forms. "However, the BMP2 gene has so far never been reported as a candidate gene for Brachydactyly type D (BDD) affecting only the thumbs." (PMID 35227291, 2022).
brachydactyly type A2 (2 papers, 2014 to 2022). Brachydactyly type A2 (BDA2) is a congenital malformation characterized by shortening (hypoplasia or aplasia) of the middle phalanges of the index finger and, sometimes, of the little finger. "The BMP2 gene, located on the long arm of chromosome 20 plays a role in bone and cartilage development and is associated with Brachydactyly type A2, an autosomal dominant disease characterized by malformations of the middle phalanx of the index finger and abnormalities of the second toe." (PMID 35227291, 2022).
brain ischemia (2 papers, 2014 to 2022). Diminished or absent blood supply to the brain caused by obstruction (thrombosis or embolism) of an artery resulting in neurologic damage. "Our screen experiment showed that most BMP family members, including BMP2, BMP4, BMP5, and BMP7 increased transiently at 24 h after brain ischemia." (PMID 34904361, 2022).